GPC3 (glypican 3)
Diseases named in the same sentence as GPC3 in open-access papers (continued):
Sharing a sentence is not in itself a finding about the gene and the disease.
tumor (continued). "To mechanistically understand the interaction of GPC3 and FAT1 in promoting HCC cell migration, we analyzed the regulation pattern of GPC3 and FAT1 on the expression of tumor metastasis-related genes under hypoxic conditions." (PMID 33420124, 2021). "Thus, while the study identifies GPC3 as a binding partner of FAT1 and presents GPC3-FAT1 as a functional complex, it opens new avenues to study underlying mechanisms that may connect FAT1 with tumor-related signaling pathways." (PMID 33878524, 2021). "GPC3-specific NK-92/9.28.z cells are functional, produced higher levels of IFN-γ and effectively lysed GPC3+ HCC cell lines in vitro, and significantly reduced the tumor growth of GPC3+ HHC in vivo." (PMID 34445750, 2021). "Over the years, additional tumor markers for HCC have been suggested, such as Golgi protein 73 (GP73), Glypican-3 (GPC3), cytokeratin 19 (CK-19), among others." (PMID 33849479, 2021). "GPC3-CAR co-expressing co-stimulatory molecule ICOSL-41BB promotes CAR T cell proliferation and tumor rejection." (PMID 34071188, 2021). "A meta-analysis found that GPC3 was highly expressed in high-grade and advanced stage HCC cells, and tumor vascular cells in HCC." (PMID 34306031, 2021). "As an oncofetal antigen, GPC3 is expressed in human embryos, participating in cell growth, differentiation, and morphogenesis, and in HCC tissues, promoting tumor growth and migration." (PMID 33420124, 2021). "We examined protein expression in B, T, and PDX samples for CCND1, KI67, CD34, GPC3, YAP, and EZH2 to provide loose validation of different tumor clusters." (PMID 34497364, 2021). "For example, silencing of GPC3 gene transcription using miR-4510 has been shown to inhibit Ras/Raf/MEK.ERK-mediated signaling and tumor growth." (PMID 33562077, 2021). "Altogether, these results point out the need for additional HL and GCT specific markers, such as CD30 and GPC3, OCT3/4, PLAP, for specific identification and classification of these two tumor subtypes, respectively." (PMID 34638431, 2021). "In previous experiments involving xenograft models of human HCC, GPC3-CAR-T cells efficiently suppressed tumor growth and impressively eradicated tumor cells that highly expressed GPC3 proteins." (PMID 34071550, 2021). "Upregulation of tumor signatures, such as GPC3, DUSP9, and CTNNB1 can be observed in tumor cells and PDX." (PMID 34497364, 2021). "The tumor tissue continuously expressed CCL19 and analyzed the tumor-suppressive effect of AAV-CCL19 on GPC3 CAR-T by in vitro and in vivo experiments." (PMID 34527749, 2021). "GPC3, as an oncofetal antigen, is overexpressed in HCC cells and involved in tumor development through Wnt, Yap, and TGFβ2 signaling pathways." (PMID 34822533, 2021). "GPC3 expression is 30-fold higher in the LIHC samples than in the non-tumor liver samples, and 8-fold higher in the UCS samples compared to the non-tumor uterus samples." (PMID 31956905, 2020). "The positive expression rates of GPC3, CK8, CK19, β-catenin, and AFP in the tumor tissue of these 42 patients were 100% (42/42), 88.1% (37/42), 92.9% (39/42), 92.9% (39/42), and 64.3% (27/42), respectively." (PMID 32195259, 2020). "These heparan sulfate modifications are not limited to GPC3, so HS20′s therapeutic potential needs to be validated due to its potential off-tumor toxicities." (PMID 32575752, 2020). "GPC3 is highly expressed in HCC and other tumor types, while its level is undetectable in normal tissues which rationalizes its use as an immunotherapeutic target." (PMID 32707982, 2020). "Tumor tissue expression of proteins AFP, TGFBR2, pSMAD2, E-cadherin, PIVKAII, cMET and Glypican-3 was analysed to determine relationship to clinical outcomes in Part A or Part B, separately or combined." (PMID 32210440, 2020). "The results of GEPIA analysis showed that expression of GPC1, GPC3, GPC4, and GPC6 was significantly higher in PDAC tumor tissues than in normal tissues (P < 0.05)." (PMID 33302876, 2020).
tumor (continued). "As a heparan sulfate proteoglycan, GPC3 interacts with different growth factors and participates in cell differentiation and migration, including of HCC tumor cells." (PMID 32443747, 2020). "In this second scenario, we have seen that both in naive tumor-free and in tumor-bearing mice, combination of vaccines (either OVA-CIRP or GPC3-CIRP) are more immunogenic in the presence of anti-CTLA-4 and anti-PD-1 antibodies." (PMID 33207844, 2020). "Immunohistochemical staining of these tumor cells revealed immunoreactivity with AFP and Glypican-3." (PMID 31898539, 2020). "Anti-GPC3 CAR T cells successfully suppressed tumorigenesis in subcutaneous tumors and significantly affected tumor growth in subcutaneous and orthotopic xenografts." (PMID 32899197, 2020). "Protein expression was quantitated using the Image J software for those markers and showed that approximately 50% of tumour sections expressed AFP and CK19 while for GPC3 it was 20% and for CD44 it was 30%." (PMID 32203212, 2020). "AUC of the existed tumor markers including AFP, GPC-3 and TGFβ1 were 0.679, 0.879 and 0.577, respectively." (PMID 33282554, 2020). "Nonetheless, findings from a recently concluded phase I trial (NCT02395250) which investigated the safety profile of glypican-3 (GPC3) CAR-T cell therapy in HCC patients showed that it was well tolerated and demonstrated indications of anti-tumor activity." (PMID 33117354, 2020). "Further, we designed a combination approach consisting of GPC3 and CD147 to mitigate off-tumor toxicity." (PMID 32968061, 2020). "The synNotch receptor logic-gated GPC3 and CD147-CAR can further mitigate on-target/off-tumor toxicity to NT in a hCD147TG mouse model." (PMID 32968061, 2020). "The effect of isoform-specific HIFα ASO treatment on HCC tumorigenesis was further investigated via assessment of hepatic mRNA expression of the HCC tumor markers α-fetoprotein (AFP) and glypican-3 (GPC3)." (PMID 33400730, 2020). "Imaging technology and immunohistochemistry together can evaluate tumor number, size, as well as the CK19/GPC3 expression preoperatively." (PMID 31676847, 2019). "GPC3 is released into the serum of HCC patients, and its utility as a tumor marker has been reported." (PMID 31024850, 2019). "Recently, GPC3 was found to be overexpressed in more than 80% of HCC and was proposed to be a promising tumor marker for the diagnosis of HCC." (PMID 31635078, 2019). "GC33, a humanized monoclonal antibody against GPC3, has been shown to induce antibody-dependent cell-mediated cytotoxicity against GPC3-positive HCC cell lines and elicit anti-tumor effects in patient-derived xenograft cancer models." (PMID 31024850, 2019). "The results demonstrated that GPC3 expression at both the protein and mRNA levels was elevated in lung SCC tissues compared with adjacent non-tumour tissues." (PMID 31160489, 2019). "To explore the function of GPC3 in the occurrence and development of lung SCC, we first compared GPC3 expression patterns in lung SCC tissue samples and matched non-tumour tissues through immunohistochemistry, Western blot (WB) and RT-PCR." (PMID 31160489, 2019). "Potent anti-tumor responses of GPC-3-specific NKs based therapeutics were observed in HCC xenografts with both high and low GPC-3 expression, which extends treatment options for patients with GPC-3+ HCC." (PMID 31500650, 2019). "On the other hand, the SR tumours from the mice treated with compound 9a showed significantly lower levels of cyclin D1 and three HCC biomarkers (α-fetoprotein, survivin and glypican 3) than those from the vehicle control-treated mice." (PMID 31754201, 2019). "In the tumor areas showing reciprocal interaction of MCT4 and GPC3, MCT4 was likely induced by the hypoxic tumor microenvironment because MCT4+ HCC cells were observed primarily in the central portions of tumor nests distant from the tumor vessels." (PMID 31706332, 2019).
tumor (continued). "A number of tumor antigens, such as human alpha-fetoprotein (AFP), GPC-3 and telomerase-reverse transcriptase (hTERT) have been identified as vaccine-based immunotherapeutic targets for HCC." (PMID 31500650, 2019). "In the acquired sorafenib resistance xenograft model, compound 9a administration decreased the growth of tumours with acquired sorafenib resistance and the expression of the HCC markers α-fetoprotein, glypican 3 and survivin." (PMID 31754201, 2019). "We previously discovered that glypican-3 (GPC3, also known as MXR7) is overexpressed in HCC and is correlated with high alpha-fetoprotein, high tumor grade, and high tumor aggressiveness." (PMID 29113314, 2017). "Immunohistochemistry studies of these 36 HCCs (tumor regions) exhibited strong positive GPC3 staining in 25 and positive IGF-1R staining in 18, and the expression of GPC3 and IGF-1R was correlated (p < 0.005 by Fisher's exact test)." (PMID 29113314, 2017). "Glypican-3 (GPC3) is well characterized as a negative regulator of cell growth and functions as a tumor suppressor protein." (PMID 28672878, 2017). "In view of the similar RFS of patients between well and moderately differentiated HCC groups, and CK19−/GPC3− andCK19−/GPC3+ groups, and two and three tumor nodules groups, similar parameters within the prognostic factors were combined into the same group." (PMID 28968990, 2017). "Glypican 3 (GPC3)-CAR T cells efficiently suppressed tumor growth in PDX3 and impressively eradicated tumor cells from PDX1 and PDX2, in which GPC3 proteins were highly expressed." (PMID 28123387, 2016). "To validate the established PDX models, we compared their morphology, immunological markers (GPC3 and AFP), and gene expressions with those of the corresponding primary tumor." (PMID 28123387, 2016). "In the present study, it was found that from CK19+/GPC3+ HCC to CK19−/GPC3+ HCC, and then CK19−/GPC3− HCC, tumor cell in intrahepatic metastasis, microvascular invasion, regional lymph node involvement, and distant metastasis was decreased." (PMID 26977595, 2016). "We found that HS20 disturbed the interaction between GPC3 and Wnt3a, blocked Wnt activation, inhibited Wnt3a-induced HCC cell proliferation and showed anti-tumor activity in mice." (PMID 27185050, 2016). "ATP1B1, GPC3, KCNIP3, and PRLR transcript levels in tumor tissues were significantly lower in PTCs than in NT, whereas LCN2, LGALS1 and SCD1 expression was upregulated in PTC compared with NT." (PMID 27249794, 2016). "To assess Notum, Glypican-1 and Glypican-3 protein localization in human CRC samples, we performed immunohistochemical analysis on 10 tumor cases and 10 normal matched mucosa specimens." (PMID 26517809, 2015). "The remaining 8 PGs, for which transcripts were expressed at a frequency of 84% (GPC1), 86% (GPC3), 88% (GPC4), 70% (GPC6), 100% (SDC1), 94% (SDC2), 93% (SDC3) and 95% (SDC4) of the tumour cases, respectively, were found to be differently modulated." (PMID 25935541, 2015). "We generated HS20, a HS-specific antibody targeting GPC3, and found that HS20 inhibited HCC tumor growth by blocking canonical Wnt-signaling." (PMID 26332121, 2015). "Next, we evaluated the expression of GPC3 in relation to the clinicopathological features, such as age, sex, AFP level and HBsAg or HCV in serum, HCC differentiation, tumor size, and metastasis." (PMID 24498024, 2014). "The four most upregulated genes were pepsinogen C (PGC), alpha fetoprotein (AFP), aldoketo reductase family 1 member B10 (AKR1B10) and glypican 3 (GPC3), which showed greater than 30-fold higher expression in HCC tumors than adjacent non-tumor tissues." (PMID 25217841, 2014). "The up to now obtained data suggest that the expression of GPC3 and GPC4 was negligibly increased in tumor as compared to normal tissues, whereas the expression of GPC5 and GPC6 was below the level of detection in both normal and cancerous breast tissues." (PMID 25140302, 2014).
tumor (continued). "Immunohistochemical panel for YST diagnosis is a combination of low molecular weight cytokeratin (CK-8, CK-18), AE1/AE3, glypican 3, CD117, CD30, AFP, PLAP, and OCT3/4, which distinguishes YST from other neoplasms." (PMID 24294529, 2013). "Further, multivariate Cox regression analysis indicated that, as for TNM stage, GPC3 staining combined with serum AFP was an independent prognostic factor for postoperative outcome and tumor recurrence in HCC patients." (PMID 23537217, 2013). "MMMT should be included in the differential diagnosis when a tumor is positive for SALL4 and/or glypican-3." (PMID 22848863, 2012). "At least one of the inhibitors GPC3, GREM1, FSTL3, and/or FST were over-expressed (FC > 1.5) in 100% of tumor samples." (PMID 23667740, 2012). "Although there was no single tumor marker, we identified a set of genes (Bone Morphogenetic Protein inhibitors GPC3, GREM1, FSTL3, and FST) in which at least one gene was over-expressed in 100% of the tumor samples." (PMID 23667740, 2012). "Because any single antigen is ubiquitously expressed in HCC, we selected AFP, GPC-3 and MAGE-1 as target antigens for DC vaccine through the analysis of the tissue array of a tumor tissues obtained from 412 patients with HCC in Korea (data not shown)." (PMID 22971679, 2012). "MMMT should be considered in the differential diagnosis when tumor is positive for both SALL4 and/or glypican-3." (PMID 22848863, 2012). "Glypican-3-CAR T cells have previously been developed as second-generation constructs, subsequently corroborated by the co-secretion of soluble cytokines like IL-15 and/or IL-21 for the improvement of anti-tumor function." (PMID 41465318, 2025). "Further examination in dual‐xenograft models indicated that locoregional administration of anti‐GPC3 CAR‐T cells exhibited significantly enhanced efficacy compared to systemic delivery, leading to substantial inhibition of tumour growth in both orthotopic and extrahepatic HCC xenografts." (PMID 41267637, 2025). "GPC3-targeting CAR-T cells with dual cytokine expression of IL-15 and IL-21 exhibited enhanced antitumour activity against HCC, demonstrating superior proliferation, persistence, and tumour regression in GPC3-positive xenograft models." (PMID 40624498, 2025). "Moreover, after co-culture with GPC3+ Huh7 cells for 3 days, SATB1-CAR-T cells exhibited reduced apoptosis levels, indicating improved resistance to tumor-induced stress." (PMID 41372119, 2025). "In our patient, tumor cells stained positive for HepPar-1, Arginase-1, and Glypican-3, but negative for CK7/CK19, excluding CCA." (PMID 40997628, 2025). "In both orthotopic and subcutaneous xenograft models, ET58-DOTA-Gd produced tumor-specific signal enhancement, in terms of intensity as well as selective prolonged retention of signals in GPC3-positive xenografts but not in GPC3-negative xenografts." (PMID 41154412, 2025). "Immunophenotypically, the tumor cells are positive for alpha-fetoprotein (AFP) and glypican-3." (PMID 40900781, 2025). "While dosimetry per se was not performed, tumor targeting and response assessment via surrogate markers support the potential of GPC3-directed radioimmunotherapy in HCC." (PMID 40722645, 2025). "The factors contributing to the conflicting conclusions in these tumor types are not yet clear, but they highlight the complex and context-dependent nature of GPC3’s role in cancer biology." (PMID 40422229, 2025). "The reasoning for the phenomenon that GPC3 levels are not correlated with tumor size, number, and distant metastasis has not been fully elucidated." (PMID 41471145, 2025).
tumor (continued). "For instance, GPC3-targeted chimeric antigen receptor (CAR) T cell therapy has shown promising safety and preliminary efficacy in early-phase clinical trials (e.g., NCT03130712, NCT05352542), demonstrating tumor infiltration and disease stabilization." (PMID 41154412, 2025). "A recent preclinical study demonstrated that GPC3-specific iNKT cells suppressed tumor progression, promoted survival, and lacked toxicity for tumor-free organs." (PMID 41465318, 2025). "Another macrophage-targeted in vivo therapy against GPC3 using mRNA/LNP technology developed by Carisma Therapeutics and Moderna has also demonstrated a similar favorable preclinical profile with potent dose-dependent cytotoxicity against GPC3+ tumor cells." (PMID 39858016, 2025). "In contrast, the systemic delivery of anti‐GPC3 CAR‐T cells via tail vein injection failed to suppress tumour growth in the large orthotopic HCC xenografts, consistent with the previous observations." (PMID 41267637, 2025). "However, CD40, glypican 3 (GPC3), Iroquois homeobox 2 (IRX2), FOXO1, EPAS1, and cyclin-dependent kinase inhibitor 1C (CDKN1C) were consistently down-regulated in tumor tissues and GbPDTOs compared to those in normal tissues." (PMID 41376821, 2025). "Tests with escalating doses of anti‐GPC3 CAR‐T cells showed a dose‐dependent increase in the treatment efficacy against orthotopic HCC tumours, with no signs of increased toxicity." (PMID 41267637, 2025). "The presence of GPC3-positive CTCs may indicate a dedifferentiated metastatic HCC, as GPC3 is predominantly found in moderately to weakly differentiated HCC tumor cells, which have a greater tendency for extrahepatic spread." (PMID 40647654, 2025). "Combining decreased tumor stiffness and increased AFP levels may provide potential valuable biomarkers for Glypican-3 (GPC3)-targeted therapy and immunotherapy." (PMID 41160615, 2025). "While the 32A9-CAR-T cells eliminated the tumor cells in vitro and encouraged the regression of HCC xenograft tumors in vivo, it was shown that the antibody-immunotoxin complex was exclusively lethal to GPC3-positive tumor cells." (PMID 40416124, 2025). "Since the intra-tumor heterogeneity of HCC and potential complications brought by liver biopsy, our clinical prediction tool identified GPC3 status satisfactorily and might be helpful in clinical decision-making." (PMID 41170458, 2025). "Within our efforts to develop GPC3-targeting radiotracers, we aimed to develop 68Ga- or 64Cu-labeled derivatives of TJ12P2 with improved tumor-to-liver contrast by identifying structure–activity relationships and investigating the human serum stability of the peptides." (PMID 41304901, 2025). "Recently, tumor vaccines are becoming a hot topic in tumor immunotherapy, and the primary tumor vaccines carried out against OCCC are Glypcan-3 (GPC3), a member of the Glypcan family acetyl heparan sulfate protein glycoprotein family, which is overexpressed in OCCC." (PMID 38347608, 2024). "Anti-HCC T-cell immunity may be elicited via the abnormal expression of oncofetal and cancer testis antigen genes (AFP, GPC3, MAGE-1 and NYESO1), viral peptide, or tumour-specific neoantigens." (PMID 39308986, 2024). "Consequently, mice treated with such LNPs generated glypican-3 (GPC3) CAR-Ms significantly in vivo, reduced tumor burden and increased survival time in an HCC mouse model." (PMID 39175095, 2024). "While this valuable work underscores the clinical translatability of radiolabeled antibodies against GPC3, there was no tumor uptake in one patient and low tumor-to-liver ratios in several others." (PMID 38978570, 2024). "A noteworthy investigation centered on CAR-T cells targeting glypican-3 (GPC3), a unique antigen commonly found in advanced HCC cases, revealed impressive antitumor effectiveness, with several patients showing marked tumor reduction and increased survival duration." (PMID 39502703, 2024).